KRAS (KRas proto-oncogene, GTPase)
Diseases named in the same sentence as KRAS in open-access papers (continued):
Sharing a sentence is not in itself a finding about the gene and the disease.
pancreatic ductal adenocarcinoma (580 papers, 2003 to 2026). An infiltrating adenocarcinoma that arises from the epithelial cells of the pancreas. "Background/Objectives: KRAS G12D is one of the most frequent oncogenic mutations in pancreatic ductal adenocarcinoma (PDAC) and remains challenging to target because of its limited druggable binding pockets." (PMID 42198429, 2026). "KRAS is the most frequently mutated oncogene in pancreatic ductal adenocarcinoma (PDAC), with a predominance of the G12D variant." (PMID 41501279, 2026). "This case of a 74-year-old woman with KRAS G12D-mutated pancreatic ductal adenocarcinoma (PDAC) and 5 liver metastases at presentation is distinguished by its exceptional clinical course and therapeutic approach." (PMID 40741546, 2025). "Over 90% of pancreatic ductal adenocarcinoma (PDAC) patients involve KRAS mutations (KRASMUT), for which current treatment options are limited." (PMID 40501736, 2025). "Mutations in KRAS are known to be a major driver in pancreatic ductal adenocarcinoma progression, and targeted anti-KRAS therapies seem to be promising." (PMID 41464573, 2025). "Given that most pancreatic ductal adenocarcinomas harbor KRAS mutations, this finding raised suspicion for metastatic disease." (PMID 40656425, 2025). "The KRAS gene is an oncogene with mutations associated with several malignancies, including bronchial adenocarcinoma, colonic adenocarcinoma, and ductal adenocarcinoma of the pancreas." (PMID 41464573, 2025). "Animal studies indicate that concurrent G-protein αs (GNAS) and KRAS mutations characterize pancreatic ductal adenocarcinomas (PDAs) arising from IPMNs, associated with the induction of lipid remodeling and fatty acid oxidation." (PMID 41181742, 2025). "KRAS mutations are nearly ubiquitous in pancreatic ductal adenocarcinoma, with a prevalence exceeding 85%." (PMID 40656425, 2025). "For instance, miR-217 role in inhibiting pancreatic ductal carcinoma was previously studied and was linked to targeting KRAS." (PMID 39920875, 2025). "We aimed to evaluate the prognostic value of the dosage of the KRAS G12 mutation, a key pancreatic ductal adenocarcinoma (PDAC) variant and to investigate the biological mechanism of the prognosis associated with the dosage of the KRAS G12 mutation." (PMID 39779977, 2025). "Approximately 94% of human pancreatic ductal adenocarcinoma (PDAC) harbor KRAS mutations, 86% of which involve a missense substitution at glycine 12 (G12)." (PMID 40906088, 2025). "Most pancreatic ductal adenocarcinomas (PDACs) harbor mutations in the KRAS gene, making it a primary therapeutic target." (PMID 40805153, 2025). "The differential association of KRAS mutations in metastatic pancreatic ductal adenocarcinoma highlights the need for more effective systemic therapies for these patients." (PMID 39777438, 2025). "KRAS mutations are instrumental in the development and progression of pancreatic ductal adenocarcinoma (PDAC)." (PMID 39810420, 2025). "Other studies have found that TIMP-1 regulated by ERK2 causedhyperproliferation of KRAS pancreatic ductal carcinoma cells." (PMID 41002380, 2025). "Recently, we conducted pilot studies to explore the therapeutic and radio-sensitizing effects of apigenin on pancreatic ductal adenocarcinoma (PDAC) cells carrying the KRAS G12D mutation, specifically PANC-1 cells." (PMID 40141193, 2025). "Research showed that over 90% of pancreatic ductal adenocarcinoma (PDAC) cases harboured KRAS mutations, which activated PI3K/AKT signalling pathways, key drivers of tumour proliferation, drug resistance and metastasis." (PMID 41006588, 2025). "KRAS is mutated in approximately 90% of pancreatic ductal adenocarcinoma (PDAC) including 35% KRASG12D, 30% KRASG12V, 15% KRASG12R, and 1-2% KRASG12C." (PMID 40247392, 2025). "KRAS mutations occur in approximately 88% of pancreatic ductal adenocarcinoma (PDAC), of which KRAS G12D comprises up to 39.5%." (PMID 40689200, 2025).
pancreatic ductal adenocarcinoma (continued). "KRAS mutations drive tumor survival, growth, and immune escape in colorectal, non-small cell lung, and pancreatic ductal adenocarcinomas by reprogramming cancer cell metabolism and reshaping metabolic interactions within the tumor microenvironment." (PMID 40303413, 2025). "One of the most commonly mutated genes in pancreatic ductal adenocarcinoma is KRAS (the Kirsten rat sarcoma viral oncogene homolog), which occurs in over 90% of cases." (PMID 40806294, 2025). "We show that the KRAS-G12C inhibitor Sotorasib synergizes with the CDK4/6 inhibitor Palbociclib to eliminate pancreatic ductal adenocarcinoma (PDAC) cells and organoids harboring KRAS-G12C mutations." (PMID 41436723, 2025). "Are specific KRAS mutations associated with different first-line treatment outcomes in metastatic pancreatic ductal adenocarcinoma?" (PMID 39777438, 2025). "This cohort study assesses the incidence of KRAS mutations and their association with clinical outcomes based on the most common treatments used in patients with pancreatic ductal adenocarcinoma." (PMID 39777438, 2025). "In pancreatic ductal adenocarcinoma, KRAS mutations dominate (~90–95%), especially at codon 12 (G12D, G12V, G12R), while NRAS and HRAS mutations are essentially absent." (PMID 41515890, 2025). "Activating somatic KRAS mutations in hotspot loci occur almost universally (> 95%) in pancreatic ductal adenocarcinoma (PDAC)." (PMID 40596921, 2025). "UCA1 expression can be upregulated by oncogenic KRAS, a major driver mutation in pancreatic ductal adenocarcinoma." (PMID 41080752, 2025). "KRAS mutations serve as key oncogenic drivers in the initiation and progression of pancreatic ductal adenocarcinoma (PDAC)." (PMID 41379561, 2025). "KRAS contains several mutation types; for instance, G12D is the most common mutation in pancreatic ductal adenocarcinoma, whereas G12C is prevalent in NSCLC." (PMID 39437162, 2025). "Pancreatic ductal adenocarcinoma is molecularly driven by KRAS mutations observed in approximately 93% of cases, most frequently at the G12D codon." (PMID 41361128, 2025). "Pancreatic ductal adenocarcinoma (PDAC) is a highly aggressive cancer with KRAS mutations in ~ 95% of cases." (PMID 41028058, 2025). "The aim of this study is to analyze the senescence-like state of after-treatment persistent cells associated with KRAS mutational status to offer a therapeutic strategy to target these cells in pancreatic ductal adenocarcinoma (PDAC)." (PMID 40382842, 2025). "Pancreatic ductal adenocarcinoma (PDAC) features KRAS mutations in approximately 90% of human cases and excessive stromal response, termed desmoplastic reaction." (PMID 39342278, 2024). "KRAS mutations are present in approximately 75% of pancreatic ductal adenocarcinoma cases and are associated with worse outcomes." (PMID 39073402, 2024). "As a result, Sotorasib and Adagrasib are now included in the NCCN (National Comprehensive Cancer Network) guidelines for treating locally advanced and metastatic pancreatic ductal adenocarcinoma (mPDAC) with KRAS-G12C mutations." (PMID 39457488, 2024). "Several prior studies have shown similar results: KRAS mutation is related to PC and is found in almost all pancreatic ductal adenocarcinomas (PDACs)." (PMID 39640479, 2024). "ATM and WEE1 (DNA damage cell-cycle checkpoint protein) inhibition has been shown to decrease CXCR2 expression and surface PDL1 exposure in human pancreatic ductal adenocarcinoma (PDAC) cells with KRAS mutations." (PMID 38473997, 2024).
pancreatic ductal adenocarcinoma (continued). "Conversely, KRAS mutations are detected early in pancreatic ductal adenocarcinomas and pancreatic intraepithelial neoplasia (PanIN) mutations in more progressed lesions are definitive precursors to the invasive disease." (PMID 38474205, 2024). "A greater percentage of pancreatic ductal adenocarcinoma patients presented detectable KRAS mutations in EV-DNA than in cfDNA." (PMID 39402599, 2024). "The KRAS proto-oncogene is a major driver of pancreatic tumorigenesis and is nearly ubiquitously mutated in pancreatic ductal adenocarcinoma (PDAC)." (PMID 38610868, 2024). "Peptide-based vaccines, such as ELI-002, are being developed to stimulate tumor-specific immune responses against KRAS mutations in pancreatic ductal adenocarcinoma (PDAC)." (PMID 39457488, 2024). "Accumulating pieces of evidence report that sotorasib is becoming resistant among NSCLC, pancreatic ductal adenocarcinoma, and colorectal adenocarcinoma patients bearing KRAS G12C mutation and even resulting in hepatotoxicity." (PMID 37396909, 2023). "The activation of mutations in KRAS, observed in more than 90 % of pancreatic ductal adenocarcinoma cases, are a critical factor involved in tumour initiation and progression." (PMID 36765737, 2023). "The presence of KRAS mutation in around 95% of pancreatic ductal adenocarcinoma (PDAC) cases has led to investigations on the relationship between p-p38 overexpression in PDAC cancer cells and patient survival." (PMID 37894916, 2023). "This investigation was supported by purifying, sequencing, and analysing clinical plasma samples for eccDNAs containing KRAS mutant alleles in 0.5 mL plasma from 16 pancreatic ductal adenocarcinoma patients and 19 healthy controls." (PMID 37602814, 2023). "Oncogenic mutations in KRAS are most frequently observed in patients with pancreatic ductal adenocarcinoma (PDAC)." (PMID 36443441, 2023). "Oncogenic KRAS is a necessary mutation for the formation of pancreatic ductal adenocarcinoma (PDAs)." (PMID 36769189, 2023). "Oncogenic driver mutations, i.e., KRAS, have been shown to reprogram multiple metabolic pathways in pancreatic ductal adenocarcinoma (PDAC) to support growth and proliferation." (PMID 37296982, 2023). "More importantly, KRAS is the most frequently mutated gene in pancreatic ductal adenocarcinoma (PDAC), showing mutations in more than 80% of patients." (PMID 37097304, 2023). "Pancreatic ductal adenocarcinoma (PAAD) harboured the most KRAS mutations (73%), followed by COAD (48%), rectum adenocarcinoma [READ] (38%), LUAD (30%), and UCEC (18%)." (PMID 37558751, 2023). "In a study in Chinese patients with advanced pancreatic ductal adenocarcinoma, patients with KRAS mutation showed worse overall survival than patients with KRAS wild-type." (PMID 36313934, 2023). "Approximately 90% of pancreatic ductal adenocarcinoma (PDAC) cases are driven by the untargetable non‐G12C KRAS mutations, and only a small subset of patients are eligible for FDA‐approved precision therapies." (PMID 36999792, 2023). "KRAS is the most common somatic mutation identified in pancreatic ductal adenocarcinoma and is seen in 90% of cases." (PMID 37366887, 2023). "RAS mutations, including KRAS, sensitize cancer cells, including pancreatic ductal adenocarcinoma (PDAC) cells, to ferroptosis induction due to mutant RAS-mediated expression of iron metabolism genes, such as Tfrc, Fth1, and Ftl59." (PMID 37845218, 2023).
pancreatic ductal adenocarcinoma (continued). "KRAS mutation is a common occurrence in Pancreatic Ductal Adenocarcinoma (PDA) and is a driver mutation for disease development and progression." (PMID 37404765, 2023). "Among these are point mutations in the KRas oncogene found in approximately 90% of pancreatic ductal adenocarcinomas." (PMID 37491420, 2023). "Mutational activation of the KRAS gene occurs in almost all pancreatic ductal adenocarcinoma (PDAC) and is the earliest molecular event in their carcinogenesis." (PMID 33833413, 2022). "For instance, KRAS G12C represents only 2% of all KRAS mutations in Pancreatic Ductal Adenocarcinoma (PDAC)." (PMID 35359456, 2022). "Kirsten rat sarcoma virus (KRAS) mutations are widespread in pancreatic ductal adenocarcinoma (PDAC) and contribute significantly to tumor initiation, progression, tumor relapse/resistance, and prognosis of patients." (PMID 36139627, 2022). "Loss of heterozygosity (LOH) for KRAS, in which a wild-type KRAS allele is progressively lost, promotes invasive and migratory abilities of pancreatic ductal adenocarcinoma (PDAC) cells and tissues." (PMID 35743139, 2022). "KRAS mutations characterize pancreatic cell transformation from the earliest stages of carcinogenesis, and are present in >95% of pancreatic ductal adenocarcinoma (PDAC) cases." (PMID 35681634, 2022). "In their protocol, owing to the high prevalence of KRAS mutations in pancreatic ductal adenocarcinoma (PDAC), the organoids are first placed in an EGF-depleted condition to enrich cancer organoids with an autonomously active EGFR-RAS pathway." (PMID 35629212, 2022). "Pancreatic Ductal adenocarcinoma (PDAC) is an aggressive cancer commonly exhibiting KRAS-activating mutations." (PMID 35454872, 2022). "KRAS is the predominant oncogene mutated in pancreatic ductal adenocarcinoma (PDAC), the fourth cause of cancer-related deaths worldwide." (PMID 34998392, 2022). "KRAS mutation is an early event and nearly a prerequisite in the pathogenesis of ductal neoplasms, including pancreatic ductal adenocarcinomas (PDAC)." (PMID 36611356, 2022). "KRAS mutations are prevalent in patients with pancreatic ductal adenocarcinoma (PDAC) and are critical to fostering tumor growth in part by aberrantly rewiring glucose, amino acid, and lipid metabolism." (PMID 35681705, 2022). "For example, activating mutations in KRAS are the most frequent alterations in pancreatic ductal adenocarcinomas (PDAC), yet inducing a Kras mutation in the epithelial cells of the pancreas of mice is insufficient to drive robust tumorigenesis." (PMID 35976056, 2022). "Molecular studies previously showed that gHRR mutations are more frequently associated to the wild-type KRAS gene, which is one of the best prognostic factors in pancreatic ductal adenocarcinoma." (PMID 33800556, 2021). "KRAS mutations are predominant in most cancers, such as pancreatic ductal adenocarcinoma (PDAC) (86%), colorectal cancer (CRC) (85%), and lung cancer (30%)." (PMID 34638560, 2021). "It has been shown that aberrant activation of the Hedgehog (Hh) and nuclear factor-kappa B (NF-κB) signaling pathways plays an important role in the pancreatic carcinogenesis, and KRAS mutation is a hallmark of pancreatic ductal adenocarcinoma (PDAC)." (PMID 34046348, 2021). "Previous studies have suggested that the vast majority of pancreatic ductal adenocarcinoma (PDAC) harbor mutations in the KRAS gene, with cfDNA mutant KRAS being an early marker of disease recurrence." (PMID 34298594, 2021). "It has been shown that KRAS mutation in pancreatic ductal adenocarcinoma (PDAC) induces transgelin-2 expression via ERK activation." (PMID 33898417, 2021).
pancreatic ductal adenocarcinoma (continued). "YAP plays a crucial role in KRAS-mutation-driven tumorigenesis of pancreatic ductal adenocarcinoma, and we previously identified that YAP/TAZ expressions participate in the resistance of anti-EGFR therapy in KRAS-mutant NSCLC." (PMID 34073318, 2021). "Mutations in KRAS are frequently found in pancreatic ductal adenocarcinoma (PDA), and expression of oncogenic KrasG12D mutation in mouse pancreatic tissue initiates the development of PDA." (PMID 34112167, 2021). "Together with other advances in this field, future directions to overcome the KRAS mutation-induced immunosuppression in pancreatic ductal adenocarcinomas are raised as well." (PMID 34069772, 2021). "Since most pancreatic ductal adenocarcinomas are caused by KRAS G12D mutation, it has been developed a biodegradable matrix to deliver KRAS siRNA-G12D (siG12D LODER)." (PMID 34863235, 2021). "The vast majority of patients with pancreatic ductal adenocarcinomas harbor KRAS mutations in their tumors." (PMID 34069772, 2021). "KRAS mutations comprise the most frequent alterations observed in pancreatic ductal adenocarcinoma (PDAC), therefore this type of cancer is considered one of the most RAS-dependent of all cancers." (PMID 34208987, 2021). "So, we used its AF (variant coverage over total coverage) to assess the purity of the tumors (AF fold 2 alleles fold 100), a method often used in pancreatic ductal adenocarcinoma with KRAS." (PMID 34301805, 2021). "Mutations which activate the members of the family can be found in as much as 20–30% of all human tumours, and mutations in the KRAS isoform can be found in 95% of pancreatic ductal adenocarcinoma and the vast majority of colon and lung tumours." (PMID 33925206, 2021). "Since activating mutations in KRAS are a hallmark of pancreatic ductal adenocarcinoma (PDAC), CRISPR/Cas was employed in a study to model complete KRAS inhibition and predict resistance mechanisms in a subset of human and mouse PDAC cells." (PMID 33117331, 2020). "For example, in a KRAS‐driven pancreatic ductal adenocarcinoma (PDAC) mouse model, oncogenic KRAS blockage cause massive tumor cell death." (PMID 34766113, 2020). "Somatic oncogenic point mutations in KRAS were proposed to be crucial to progression and drug resistance in 90% of patients with pancreatic ductal adenocarcinoma, a highly metastatic disease with a high mortality rate." (PMID 32723974, 2020). "This meta-analysis aims to identify the diagnostic accuracy of mutations in the Kirsten Rat Sarcoma (KRAS) oncogene in the diagnosis of pancreatic ductal adenocarcinoma (PDAC)." (PMID 32825312, 2020). "To determine if MiR181ab1 plays a functional role in other oncogenic KRAS–driven cancers, we evaluated its role in pancreatic ductal adenocarcinoma (PDAC), a highly lethal cancer in which KRAS mutations are present in over 90% of cases." (PMID 31874105, 2020). "Pancreatic ductal adenocarcinoma is a highly metastatic disease associated to KRAS Proto-Oncogene, GTPase (KRAS) gene mutations, occurring to > 90% of the patients." (PMID 32370160, 2020). "KRas has been implicated in difficult-to-treat cancers such as pancreatic ductal adenocarcinoma (PDAC) and has therefore been thoroughly studied." (PMID 32511232, 2020). "Undifferentiated carcinomas occur more frequently in the pancreas and contain the same KRAS mutation as that in pancreatic ductal adenocarcinoma, suggesting that the two components have a common origin." (PMID 32487254, 2020).